FNDC5 (fibronectin type III domain containing 5)
Diseases named in the same sentence as FNDC5 in open-access papers (continued):
Sharing a sentence is not in itself a finding about the gene and the disease.
type 2 diabetes mellitus (28 papers, 2014 to 2025). A type of diabetes mellitus that is characterized by insulin resistance or desensitization and increased blood glucose levels. "The polymorphism in the gene encoding irisin (FNDC5 rs1746661) has been identified to be related to high systolic blood pressure and dyslipidemia in female patients with type 2 diabetes (T2DM)." (PMID 38405155, 2024). "Despite these reports, to the best of our knowledge, the relationship between variants of FNDC5 and the risk of type 2 diabetes and related clinical parameters in the Chinese population has not been previously evaluated." (PMID 25369206, 2014). "In the present study, three tagging SNPs in the region of the FNDC5 gene, which encodes the myokine irisin, were tested for their association with type 2 diabetes and related quantitative traits in a Chinese Han population." (PMID 25369206, 2014). "Therefore, it is imperative to extend studies of the influence of FNDC5 variants on type 2 diabetes and metabolic traits in other Chinese populations." (PMID 25369206, 2014). "Clinical studies combined with cellular experiments revealed that FNDC5 mRNA was decreased in adipose tissue of patients with type 2 diabetes." (PMID 33817324, 2021). "It is worth noting that myotubes from patients with type 2 diabetes expressed and secreted the highest levels of FNDC5 mRNA and irisin, respectively, resembling our finding in DM2 patients." (PMID 29184538, 2017). "In a study by Kurdiova, glucose decreased the in vitro expression of Fndc5 in myotubes in which the levels of Fndc5 mRNA were lower in adipose tissue and plasma in type 2 diabetes patients versus pre-diabetic individuals." (PMID 28445520, 2017).
Cognitive impairment (22 papers, 2018 to 2026). Abnormal cognition is characterized by deficits in thinking, reasoning, or remembering. "Thus, our study revealed that through regulating microglial activation, FNDC5/irisin improved the II/R-induced neuroinflammation, oxidative stress, and neuronal loss, which further improved cognitive deficits, a newly discovered potential therapeutic target." (PMID 40388874, 2025). "A clinical cross-sectional study has shown that genetic variations in FNDC5 are associated with reduced brain glucose metabolism in patients with cognitive impairment, suggesting that FNDC5 may participate in brain metabolic regulation in regions susceptible to AD pathology (Ref." (PMID 40660735, 2025). "Finally, we further explored the underlying mechanisms and elucidated that the PGC-1α/FNDC5 pathway might be responsible for depression with co-morbid cognitive impairment." (PMID 37266540, 2023). "As expected, inhibition of FNDC5/irisin in the brain led to cognitive impairment and muscle attenuation." (PMID 40344642, 2025). "The treatment normalized hippocampal FNDC5/irisin expression, which was associated with a reduction in Aβ and P-tau proteins, improved BDNF and insulin signaling, and alleviated cognitive impairments." (PMID 40018518, 2025). "It alleviated PD-related pathological impairments and cognitive deficits and promoted the secretion of FNDC5 and BDNF, producing neuroprotective effects." (PMID 41195080, 2025). "Our findings suggested that FNDC5/irisin contributed to the improvements in cerebral injury and cognitive deficits mediated by microglia after II/R." (PMID 40388874, 2025). "In conclusion, our results encourage further investigations suggesting FNDC5/irisin pathway as a potential target for therapeutic strategies to counteract cognitive impairment in AD patients." (PMID 40560607, 2025). "Accumulating evidence has demonstrated that FNDC5/irisin plays a pivotal role in synaptic plasticity, neurogenesis, and cognitive deficit in neurodegenerative diseases." (PMID 40388874, 2025). "Knockout (FNDC5/irisin KO) mice exhibit cognitive deficits in object recognition, spatial learning, and fear conditioning tasks, while direct injection of FNDC5/irisin into the lateral ventricle of AD mice enhances memory." (PMID 40427436, 2025). "Knockdown of PGC1α in the mouse brain also led to accelerated cognitive impairment and muscle attenuation, along with decreased FNDC5/irisin expression and protein levels in the hippocampus." (PMID 40344642, 2025). "While the deletion of irisin through the global deletion of FNDC5 leads to cognitive disorders and memory disorders in the elderly." (PMID 37600508, 2023). "In patients with AD, levels of FNDC5/irisin are lower in hippocampi and CSF compared with healthy individuals or patients with mild cognitive impairment." (PMID 35661882, 2022). "In a rat model of AD, direct intervention in the hippocampus with the 42 amino acid form of amyloid β (Aβ1–42) resulted in cognitive impairment by suppressing PGC1α/FNDC5/BDNF signaling." (PMID 35764750, 2022). "We specifically knockout FNDC5/irisin in mice, and showed that II/R in Fndc5−/− mice worsened pathologic alternations of the hippocampus and cognitive deficit, accompanied by graver neuroinflammation, oxidative stress, neuronal loss, including apoptosis and ferroptosis." (PMID 40388874, 2025). "Our findings demonstrated that treadmill exercise could effectively alleviate cognitive disorders via the activation of the FNDC5–BDNF pathway and enhance the dopaminergic synaptic connection from SNpc to the hippocampus in the MPTP-induced chronic PD model." (PMID 37175535, 2023). "However, the cognitive impairment was partially reversed by moderate physical activity, revealing a recovered PGC1α/ FNDC5/BDNF pathway." (PMID 35764750, 2022).
Cognitive impairment (continued). "Thus, FNDC5/irisin acted as a messenger of muscle brain cross talk, influencing the neurogenesis in cognitive impairment, in particular through the neuroprotective effects of BDNF." (PMID 35431908, 2022). "This review delves into the positive effects of irisin on cognitive impairment, examines the signalling pathways related to fibronectin type III domain-containing 5 (FNDC5)/irisin and provides future perspectives for research on the anti-cognitive impairment effects of irisin." (PMID 40660735, 2025). "Mechanistically, using genetic interference or knockout techniques targeting Fndc5, we revealed hippocampal Fndc5/irisin may mediates the beneficial effects of LIPUS on hippocampal damage and cognitive deficits in experimental VaD." (PMID 36823656, 2023). "Also, we do not know if the gut flora affects cognitive deficits in PD patients by promoting FNDC5 production." (PMID 41195080, 2025). "Furthermore, another group reported that moderate treadmill exercises could ameliorate Aβ deposition and cognitive impairment, possibly due to the PGC-1α/FNDC5/BDNF pathway." (PMID 30355327, 2018). "Here, we studied the influence of a SNP found in an intronic region of the FNDC5 locus (rs1746661) on AD biomarkers and FDG-PET in a cohort of human subjects with or without cognitive impairment." (PMID 37601408, 2023).
hepatocellular carcinoma (13 papers, 2017 to 2025). A malignant tumor that arises from hepatocytes. "A recent study implied that M2 macrophage polarization induced by FNDC5 was associated with hepatocellular carcinoma cell growth." (PMID 37874682, 2023). "Therefore, we investigated the genetic and epigenetic regulation mechanisms of this hormone by using several human tissue samples and hepatocellular carcinoma cell lines that differentially express FNDC5 variants genes." (PMID 28240298, 2017). "The results showed that hepatocellular carcinoma tissues have higher FNDC5 expression than normal tissues, which can be reduced by knockdown or overexpression of FNDC5." (PMID 39315094, 2024). "Based on this screening result, we selected hepatocellular carcinoma cell lines in the proceeding studies to discriminate the transcriptional regulation mechanism of FNDC5." (PMID 28240298, 2017). "In fact, there are reports of elevated expression of FNDC5/irisin in human hepatocellular carcinoma (HCC) and our bioinformatic analysis also indicates that high expression of both GADD45β and FNDC5 negatively impacts the prognosis of cancer patients." (PMID 37746289, 2023). "This is particularly shown in hepatocellular carcinoma (HCC) whereby, the increased hepatic mRNA levels of FNDC5/irisin in HCC patients correlated with increased expression of proinflammatory markers, such as IL-6 and TNF-α." (PMID 33614663, 2021). "Among the tested cell lines, most human hepatocellular carcinoma cells (HepG2, Hep3B, Sk-Hep1, and SNU449) exhibited high mRNA levels of the FNDC5 variants, although Huh7 cells did not." (PMID 28240298, 2017).
depression (12 papers, 2021 to 2025). "In brief, research findings suggest that a decrease in central FNDC5/irisin may be a common pathological mechanism underlying both depression and AD." (PMID 38985081, 2024). "Therefore, in our present study, we used a chronic unpredictable mild stress- (CUMS-) induced depression model to investigate whether the antidepressant-like effects of CUR are associated with the activation of the PGC-1α/FNDC5/BDNF pathway." (PMID 34950248, 2021). "We conducted a thorough search of PubMed publications from 2012 to 2024 using the following keywords: exercise, FNDC5, irisin, depression, central nervous system, and neuroprotection." (PMID 39484160, 2024). "The serum level of PGC-1α was significantly downregulated in MDD patients (1.070 ± 0.151 in HCs and 0.667 ± 0.253 in depression, p < 0.01), whereas FNDC5 levels remained stable (1.256 ± 0.226 in HCs and 1.509 ± 0.442 in depression, p > 0.05)." (PMID 37266540, 2023). "Considering the role of BDNF in the inhibition of depression, PGC1a/FNDC5/BDNF has been determined to be a critical pathway for neuroprotection; as such, it is expected to be an effective target for therapeutic interventions in depressive disorders." (PMID 34950248, 2021). "FNDC5/irisin knockout mice have dysbiosis of the gut microbiota, with a decrease in the Firmicutes and an increase in the Bacteroidetes, and exhibit anxiety and depression-like behaviors." (PMID 41459223, 2025). "Moreover, FNDC5 expression declined in the frontal cortex of male mice with lipopolysaccharide-induced depression, while it was unaltered in the hippocampus." (PMID 38985081, 2024). "Correlation analysis between FGF 19 and PGC-1α/FNDC5 in depression." (PMID 37266540, 2023). "Upregulation of FNDC5/irisin may thus represent a potential therapeutic target for depression." (PMID 37789092, 2023). "This is an unexpected result, as reduced expression of FNDC5/irisin, and BDNF has been observed in patients suffering from depression and in some animal models of depression." (PMID 38194217, 2024). "It is widely accepted that regular PA stabilizes or reduces depression and anxiety levels, enhancing the activity of the PGC-1α/FNDC5/Irisin pathway, which in turn promotes neuronal survival." (PMID 37761690, 2023). "However, whether brain FNDC5/irisin expression is altered in depression remains elusive." (PMID 36697257, 2023). "The second studied pathway, FNDC5/irisin/BDNF, which can be stimulated by PGC1α and physical activity, did not seem to play a significant role in disturbances occurring in the used model of depression." (PMID 38194217, 2024). "Therefore, exercise can ameliorate depression by upregulating PGC-1α, FNDC5, and BDNF expression." (PMID 37239191, 2023).
memory impairment (11 papers, 2019 to 2025). "Their research further demonstrated that elevating FNDC5 levels within the brain or peripherally had a mitigating effect on synaptic and memory impairments in AD mouse models." (PMID 38260156, 2023). "A daily swimming programme (1h per day, 5days per week for 5weeks) protected mice from amyloid-β oligomers (AβOs)-induced memory impairment and decrease in the expressions of Fndc5 mRNA and irisin protein in mouse hippocampus." (PMID 36267573, 2022). "In the brain of Fndc5 −/− mice, a mice mole of AD, synaptic plasticity and long-term potentiation are compromised, while the FNDC5/irisin re-expression rescued synaptic plasticity and memory impairment." (PMID 33672427, 2021). "Surprisingly, increased FNDC5/irisin levels promoted improved synaptic plasticity and counteracted memory impairment, highlighting the protective role of exercise in neurodegeneration." (PMID 34940510, 2021). "However, elevating FNDC5/irisin levels in the brain or peripheral blood can enhance synaptic plasticity and alleviate memory impairments in AD mouse models." (PMID 40677895, 2025). "Noteworthily, increased brain levels of FNDC5/irisin restored synaptic plasticity and prevented memory impairment, suggesting that increasing irisin levels, either pharmacologically or through exercise, is a new therapeutic strategy to counteract cognitive decline in AD." (PMID 36142305, 2022). "In addition, overexpression of irisin in the brain suppressed neuroplasticity defects and memory impairment in AD model mice, and intraperitoneal injection of anti-FNDC5 eliminated the beneficial effect of exercise on AD-like phenotype." (PMID 34071457, 2021). "In addition, it has been reported that damage to mitochondrial quality control contributes to CNS disease while boosting either brain or peripheral FNDC5/irisin levels attenuates synaptic and memory impairments in AD mouse models, suggesting a potential neuroprotective role." (PMID 38802337, 2024). "Furthermore, forced peripheral expression of FNDC5/irisin rescues memory impairment." (PMID 33562601, 2021).
metabolic syndrome (10 papers, 2017 to 2025). A cluster of metabolic risk factors for CARDIOVASCULAR DISEASES and TYPE 2 DIABETES MELLITUS. "Our grouphas previously identified an association between two polymorphisms in the geneencoding irisin, FNDC5, and increased HbA1c, higher systolic bloodpressure, and dyslipidemia in women with T2D." (PMID 40643080, 2025). "Fibronectin type III domain–containing protein 5 (FNDC5) and its derived hormone, irisin, have been associated with metabolic control in humans, with described FNDC5 single nucleotide polymorphisms being linked to obesity and metabolic syndrome." (PMID 37601408, 2023). "As a transmembrane protein present in various tissues including heart, liver, skeletal muscle, and adipose tissue, FNDC5, the precursor of irisin, was found to be a novel player in metabolism and metabolic syndrome." (PMID 33817324, 2021). "Independently of its function as precursor or irisin, FNDC5 has been recently shown as relevant for the regulation of diverse upstream and downstream signaling pathways involved in metabolic syndrome." (PMID 33198247, 2020).
atherosclerosis (9 papers, 2017 to 2023). A disease characterized by the build-up of fatty material and calcium deposition in the arterial wall resulting in partial or complete occlusion of the arterial lumen. "Except for the beneficial role in metabolic disorders, recent studies also implicated that FNDC5/Irisin was involved in regulating various cardiovascular diseases, such as atherosclerosis, hypertension, myocardial ischemia/reperfusion injury, and cardiac hypertrophy." (PMID 31209361, 2020). "In atherosclerosis, FNDC5 inhibited ox-LDL-induced foam cell formation and monocyte adhesion in vascular smooth muscle cells (VSMCs)." (PMID 34206655, 2021). "Besides these effects, FNDC5 regulates various cardiovascular diseases such as atherosclerosis, myocardial ischemia/reperfusion injury, cardiac hypertrophy, and hepatic affections such as fatty liver diseases, impaired fatty acid oxidation, and autophagy in the hepatic tissue." (PMID 37408184, 2023). "In this study, we show that atherosclerosis was suppressed in the ApoE-KO/PGC-1α mice, and the mRNA expression levels of FNDC5 and the genes involved in BAIBA biosynthesis in skeletal muscle were increased about 2-fold in the ApoE-KO/PGC-1α mice." (PMID 30858489, 2019). "Our results suggest the need for further investigation on the possible influence of FOXO3A/FNDC5 interactions and APOE/FNDC5 interactions with EL, but also with other age-related diseases such as atherosclerosis, Alzheimer’s, or Parkinson’s disease." (PMID 29143599, 2017).
cardiac hypertrophy (9 papers, 2019 to 2025). "Taken together, these results indicate that FNDC5 deficiency was associated with deterioration in myocardial hypertrophy in response to HFD." (PMID 30940158, 2019). "FNDC5 overexpression alleviated HFD-induced cardiac hypertrophy evidenced by reduced Nppa, Nppb, Myh7 mRNA level and cardiomyocytes area." (PMID 30940158, 2019). "The therapeutic effects of lentiviral vector-mediated FNDC5 overexpression were also examined in HFD-induced cardiac hypertrophy." (PMID 30940158, 2019). "FNDC5 overexpression attenuated cardiac hypertrophy as well as cardiac inflammation and oxidative stress in HFD-fed mice." (PMID 30940158, 2019). "The primary novel findings in our study are that FNDC5 deficiency deteriorates, while FNDC5 overexpression attenuates HFD-induced cardiac hypertrophy, cardiac inflammation and oxidative stress." (PMID 30940158, 2019). "FNDC5 ameliorated HFD-induced cardiac hypertrophy, via the effects on inflammation, oxidative stress and NFκB activation, in association with JAK2/STAT3 signaling inhibition." (PMID 30940158, 2019). "The effects of FNDC5 absence on cardiac inflammation further urged us to determine the possible therapeutic roles of FNDC5 in HFD-induced cardiac hypertrophy." (PMID 30940158, 2019). "FNDC5−/− mice were used to determine the roles of FNDC5 in HFD-induced myocardial hypertrophy in the present study." (PMID 30940158, 2019). "Notably, TAC- or AngII-induced cardiac hypertrophy elevates FNDC5 expression, resulting in increased Irisin protein." (PMID 40001564, 2025). "Elucidation of the precise molecular mechanisms underpinning FNDC5 signaling involved in the cardiac hypertrophy process may prove useful in understanding the role of FNDC5 in metabolic-related cardiovascular diseases." (PMID 30940158, 2019). "Chen et al24 revealed that intraperitoneal injection of recombinant (r)‐irisin or overexpression of FNDC5 in T2DM mice reduced mitochondrial fission and caspase‐dependent cardiomyocyte death, subsequently alleviating cardiac hypertrophy and fibrosis." (PMID 37721125, 2023). "In a model of cardiac hypertrophy, induced by transverse aortic constriction (TAC), significantly elevated levels of ANP were found in the hearts of wild-type mice, while even higher levels were observed in FNDC5 knockout mice." (PMID 39856994, 2025). "According to our in vitro and in vivo data, FNDC5 absence/knockdown led to an enhanced phosphorylation level of JAK2 and STAT3 under high lipid treatment (HFD/PA) accompanied by aggravated inflammation, oxidative stress and cardiac hypertrophy." (PMID 30940158, 2019).
chronic kidney disease (9 papers, 2014 to 2025). Impairment of the renal function secondary to chronic kidney damage persisting for three or more months. "Irisin (gene name: Fndc5), a novel myokine that positively regulates muscle mass, was recently shown to ameliorate chronic kidney disease-induced muscle wasting through the inhibition of fatty acid metabolism." (PMID 41249735, 2025). "Mechanistically, chronic renal failure can induce skeletal muscle atrophy in mice by inhibiting FNDC5 expression and enhancing skeletal muscle autophagy." (PMID 38405155, 2024). "A previous study conducted in patients with chronic renal failure, irisin levels were determined to be negatively correlated with creatinine, which is considered to result from the inhibition of FNDC5 by indoxyl sulphate which is a uremic toxin." (PMID 31881940, 2019). "Serum FNDC5/irisin levels have previously been investigated in obesity, chronic kidney disease, type 2 diabetes mellitus and various types of cancer." (PMID 29522296, 2018).